EPM2A (EPM2A glucan phosphatase, laforin)
Diseases named in the same sentence as EPM2A in open-access papers (continued):
Sharing a sentence is not in itself a finding about the gene and the disease.
steatosis (1 paper, 2025). Increased lipid within the cytoplasm of cells. "We examined potential liver‐related adverse effects, specifically lobular inflammation and hepatic steatosis in WT, Epm2a−/− and Epm2b−/− mice, 5 months after IV injection of the rAAVP31‐Null, rAAVP31‐hEPM2A, or rAAVP31‐hEPM2B vectors, using H&E staining." (PMID 41169091, 2025). "No lobular inflammation, ALT/AST elevation, steatosis, or hepatocyte hypertrophy was observed in treated or untreated WT, Epm2a−/− or Epm2b−/− mice, except for mild lobular inflammation in Epm2a−/− and Epm2b−/− mice injected with the rAAVP31‐Null vector." (PMID 41169091, 2025).
tonic-clonic seizures (1 paper, 2014). "In this study, we analyze the sensitivity of Epm2a−/− and Epm2b−/− mice to the convulsant drug pentylenetetrazol (PTZ), an antagonist of the γ-aminobutyric acid type A (GABAA) receptor, commonly used to induce epileptic tonic-clonic seizures in laboratory animals." (PMID 25309313, 2014).
tumor (6 papers, 2020 to 2025). "This evidence suggests that EPM2A gene expression has diagnostic potential in early tumor detection, can reflect the progression trend and may become a novel therapeutic target." (PMID 36199693, 2022). "In our study, the lower expression of EPM2A was also associated with several factors that adversely affect the prognosis in the TCGA cohort, such as a larger tumor size, advanced clinical stage, extrascleral extension, and a heavier infiltration with macrophages." (PMID 32751097, 2020). "The results showed decreased expression of EPM2A in 95.65% of tumor tissues and was related to their prognosis, especially PCA (p = 0.008, HR = 0.57, 95% CI: 0.371–0.863)." (PMID 36199693, 2022). "Further validation of the deceased expression of EPM2A in tumor vs. paired adjacent tissues was performed with pancancer data from TCGA project (p < 0.05)." (PMID 36199693, 2022). "We confirmed the decreased expression of EPM2A by IHC, and more experiments will be performed to determine the expression pattern in tumor and normal tissues in PCA." (PMID 36199693, 2022). "Immunohistochemistry was used to validate the different transcript levels of EPM2A between tumor and normal tissues." (PMID 36199693, 2022). "Our results are supported by previous research demonstrating the mechanisms of EPM2A in inhibiting tumor development." (PMID 36199693, 2022). "EPM2A is depressed in most human lymphomas and acts as a tumor suppressor in immunocompromised hosts by dephosphorylating the essential component of the Wnt signaling pathway, GSK-3β." (PMID 36199693, 2022). "In this study, to investigate the prognostic significance of EPM2A, we first compared the expression pattern among tumor and adjacent tissues in 22 tumors." (PMID 36199693, 2022). "Tumors with the largest basal diameter above 13 mm exhibited a decline in BAP1, EPM2A, GYG1, GYG2, and PPP1R3C levels, whereas only EPM2A was negatively associated with an increased tumor thickness." (PMID 32751097, 2020). "In addition, we investigated the clinicopathological feature distributions between the high and low EPM2A subgroups, and the results showed that patients with low EPM2A expression levels had higher Gleason scores and tumor stages." (PMID 36199693, 2022).
cancer (4 papers, 2014 to 2025). A tumor composed of atypical neoplastic, often pleomorphic cells that invade other tissues. "In this study, we first conducted a pancancer analysis to reveal the differential expression of EPM2A in 22 cancers." (PMID 36199693, 2022). "Decreased EPM2A was observed in most cancer types, and the decreased expression level was highly related to unfavorable OS and PFS, especially in PCA." (PMID 36199693, 2022). "Next, the cancer antitumour mechanisms of EPM2A were further investigated with enrichment analysis." (PMID 36199693, 2022). "The protein coding genes ZNRD1, RNF39 and PPP1R11, along with the ncRNA ZNRD1-AS1, have been associated with disease states that are related to autoimmunity, immunity, and infection; while EPM2A and SHPRH have been associated with glycogen metabolism, cancer, and chemical dependency." (PMID 25642351, 2014).
EPM2A also shares sentences with these, for which no sentence is quoted: Progressive myoclonic epilepsy (4 papers); neurodegenerative disease (3); neurological disorders (3); cognitive decline (2); endometrioid carcinoma (2); Parkinsonism (2); Alzheimer disease (1); autism (1); childhood dementia (1); colorectal cancer (1); endometrial carcinoma (1); Fanconi anemia (1); gastric cancer (1); genetic disorder (1); infantile epilepsy (1); infection (1); lactic acidosis (1); liver cancer (1); lymph node metastasis (1); MELAS (1); memory (1); mental retardation, X-linked 21 (1); Mitochondrial encephalopathy (1); myoclonic epilepsy (1); Myoclonus (1); polyneuropathy (1); Premature ovarian insufficiency (1).